IL6 (interleukin 6)
Diseases named in the same sentence as IL6 in open-access papers (continued):
Sharing a sentence is not in itself a finding about the gene and the disease.
breast cancer (continued). "Importantly, a recent study has also suggested a crucial role for increased IL‐17 levels in murine breast cancer metastasis to bone/lung, perhaps through altered IL‐6 and/or chemokine expression." (PMID 26725371, 2016). "Additional studies into the effects of IL-6 blockers in breast cancer are thus warranted and could offer exciting new directions for treatment." (PMID 26840088, 2016). "One randomized clinical study indicated that psychological stress could alter the level of MDSCs in breast cancer cells via the upregulation of IL-1Rα, IP 10, G-CSF, and IL-6." (PMID 27542274, 2016). "In addition, the inhibition of SDF-1, IL-6 or both in SFCM collected from TCF-169-CHEK2-siRNA reduced the invasion potential of breast cancer cells 2.5, 5 and 6 fold, respectively." (PMID 27484185, 2016). "In addition, IL-6 has been shown to be a direct regulator of the self-renewal of breast cancer stem cells as mediated by the IL-6 receptor/GP130 complex through STAT3 activation." (PMID 27462787, 2016). "Additionally, STAT3 has been reported to be overexpressed in nearly 40% of all breast carcinomas due, in part, to autocrine expression of IL-6." (PMID 27190500, 2016). "In breast cancer model EMT triggered the release of soluble mediators (IL-6, IL-8, sICAM, PAI-1 and GM-CSF) which induced angiogenesis and recruited MDSCs which might favour cancer spread." (PMID 27886105, 2016). "A recent report identified IL-6 as a target of Notch in breast cancer cells." (PMID 25669984, 2015). "Autocrine IL-6 have been confirmed in lung cancer cells and breast cancer cells." (PMID 25504436, 2015). "Similarly, IL-6 stimulation of CD44-CD24+ breast cancer patient derived cells has been demonstrated to reduce E-cadherin expression and generate a CD44 + CD24- population." (PMID 26522776, 2015). "Our findings on basal-like breast carcinomas support the hypothesis that IL-6 gene expression is related to breast cancer stem cell phenotype." (PMID 25881039, 2015). "High serum levels of interleukin-6 correlate with poor outcome in breast cancer patients." (PMID 25881039, 2015). "High SRF–YAP/TAZ expression is correlated with IL6-enriched MaSC/basal-like breast cancer (BLBC)." (PMID 26671411, 2015). "Members of the interleukin-6 (IL-6) family, which are induced in a paracrine/autocrine fashion in breast cancer, mediate the activation of the Janus Kinase 2 (JAK2) and of the signal-transducer and transcription factor 3 (STAT3) promoting the expansion of mammary CSCs." (PMID 25774169, 2015). "Similarly, Tai chi increased IL-6 and decreased IL-2 levels which was positively related to an improvement in QoL in breast cancer patients." (PMID 26498685, 2015). "Also, IL-6 is capable of generating CD44+ cells with stem-like properties through induction of the EMT in the T47D breast cancer cell line." (PMID 25590298, 2015). "Breast cancer cells overexpressing YB-1 had increased IL-6 production." (PMID 26512918, 2015). "Indeed, IL-6 has been shown to promote invasion capability and is a marker for poor outcome in breast cancer patients and increased IL-6 serum levels are associated with increased metastatic spread." (PMID 26000019, 2015). "Mesenchymal stem cell derived IL6 protein promotes breast cancer cell migration and invasion." (PMID 26173622, 2015). "In addition, the elevated expression of pro-inflammatory cytokines such as TNFα, IL-1 and IL-6 in breast cancer is directly correlated with the metastatic behavior and progression of breast carcinomas." (PMID 26460736, 2015). "Therefore, higher expression of miR-146b was positively correlated with patient survival in breast cancer subtypes with increased IL6 expression and STAT3 phosphorylation." (PMID 26697428, 2015). "However, their specific role in breast cancer is still poorly understood, even though some of the mediators such as IL-6 and TGF-β1 seem to be clearly involved in progression of breast malignancies into a more malignant phenotype." (PMID 26000019, 2015).
breast cancer (continued). "In addition, Her2 specific antibodies have been used to target breast cancer stem cells while IL-6 antibodies have been used in head and neck squamous cell carcinomas." (PMID 26449187, 2015). "LPA1 is a well-known inducer of IL-6 and IL-8 secretions in ovarian and breast cancer cells." (PMID 26098771, 2015). "In addition to inhibiting apoptosis, IL6 signaling is also known to promote migration and invasion in a great variety of tumors including ovarian cancer, breast cancer, glioblastoma and chondrosarcoma." (PMID 26215971, 2015). "The good correlation of IL-6 level and poor clinical outcome of lung cancer, breast cancer and pancreatic cancer patients indicates that IL-6 might be a pivotal molecule to overcome inflammation-correlated lung cancer metastasis." (PMID 26528698, 2015). "In breast cancer, it has recently been shown that IL-6 contributes to tumor progression." (PMID 25599228, 2015). "These clinical associations are corroborated by emerging preclinical data revealing that IL-6 is a potent growth factor and promotes an epithelial-mesenchyme (EMT) phenotype in breast cancer cells to indicate that IL-6 in the breast tumor microenvironment is clinically relevant." (PMID 25881039, 2015). "Besides, several types of cancer cells including breast cancer cells and lung cancer cells produce their own IL-6, which acts in an autocrine manner to mediate cancer promotion." (PMID 25504436, 2015). "The reduced effect of subcutaneous ASCs might be explained by a reduced expression of various cytokines like IL-6 and IL-8 known to be involved in breast cancer proliferation." (PMID 26439686, 2015). "Since paracrine roles of IL6 protein are relatively less understood, our data suggest that IL6 mRNA expressed by basal tumor cells can play a role in paracrine activators for other types of breast cancer cells (e.g., luminal) or stromal cells." (PMID 26173622, 2015). "TCC practice in breast cancer survivors significantly enhanced functional capacity and health-related life quality, decreased fat mass with increased IL-6 and decreased IL-2 levels, and maintained insulin level compared to the breast cancer survivors only receiving psychosocial support." (PMID 25653009, 2015). "Finally, fatigued breast cancer survivors had greater increased LPS-stimulated IL-1β (beta) and IL-6 production from baseline to 30 min after the Trier Social Stress Task (a standardized laboratory stressor) than non-fatigued survivors." (PMID 26247972, 2015). "Here, we show that direct interplay between YB-1 and IL-6 regulates breast cancer metastasis." (PMID 26512918, 2015). "Thus, IL-6 is capable of generating CD44+ cells with stem-like properties through induction of EMT in the epithelial-like T47D breast cancer cells." (PMID 25590298, 2015). "We also find that IL-6 mRNA levels are readily detected ex vivo only in CK-5 positive basal-like breast carcinoma tissues, an uncommon form of biological aggressive breast carcinoma with stem-cell-like features, including high levels of CD133 and CD44 expressions." (PMID 25881039, 2015). "IL-6 mRNA is detectable only in basal-like breast carcinoma tissues; our results reveal that IL-6 triggers a Notch-3-dependent upregulation of the Notch ligand Jagged-1, whose interaction with Notch-3 promotes the growth of MS and Michigan Cancer Foundation-7 (MCF-7)-derived spheroids." (PMID 25881039, 2015). "BMDMs exposed to 4T1 mammary carcinoma-conditioned medium demonstrated enhanced production of pro-inflammatory cytokines tumor necrosis factor α, interleukin-6, and CCL2 in response to lipopolysaccharide (LPS) while production of interleukin-10 remained unchanged." (PMID 26177198, 2015). "One of the major pathways to increased pStat3 levels in breast cancer cells involves IL-6; thus, the studies summarized above provide a possible mechanism to explain our finding of increased pStat3 levels in breast cancers expressing increased levels of Stat3β." (PMID 25268166, 2014).
breast cancer (continued). "In several studies, the IL-6 level has been related to fatigue in breast cancer patients during RT, although, this association was not confirmed by others." (PMID 24800238, 2014). "While knockdown of SIRT1 had no major effect on IL-6 expression in breast cancer cells, ERα-driven control of the association of SIRT1 with chromatin contributes to SIRT1 activity in other contexts." (PMID 24771768, 2014). "Also both TPA and IL-6 serum level are highly sensitive in detecting breast cancer and the combination of the two tumor markers will increase the specificity for detecting breast cancer up to 96.7%." (PMID 25225536, 2014). "Furthermore, our demonstrated regulatory role of ezrin in the expression of IL-6 is highly relevant as high levels of IL-6 correlate with increased metastatic potential and poor outcome in breast cancer." (PMID 25231728, 2014). "LPA1 was shown to induce the secretion of IL-6 and IL-8 in ovarian and breast cancer cells." (PMID 24828490, 2014). "IL-6 contributes to lung and breast cancer cell malignancy and effusion, and IL-6 and IL-10 may bias the induction of the immune response and lead to a state of tolerance against tumors." (PMID 25299052, 2014). "Interestingly, previous studies also demonstrated that IL-6 contributes to many age-related pathologies, including late life cancers, and IL-6 secreted from MSCs has been regarded as a crucial cytokine for breast cancer cell metastasis." (PMID 25419563, 2014). "Furthermore, only in ER+ breast cancer patients, we also demonstrated a positive relationship of BMI, leptin, with IL-6." (PMID 25338520, 2014). "Indeed, it has been previously shown a causal role of p16 disruption in modulating DNA hypermethylation, and the role of IL-6 in controlling methylation in breast cancer cells." (PMID 24595168, 2014). "This study investigated whether breast cancer patients exposed to local radiotherapy showed lower cognitive function mediated by higher plasma interleukin (IL)-6 levels than those unexposed." (PMID 24756915, 2014). "On the other hand, BOKL in contact with fibroblasts showed a significantly higher (p < 0.001) proliferation, accordingly to literature results showing how the release of specific factors (such as interleukin-6) by fibroblasts can increase the growth of breast cancer cells." (PMID 25335447, 2014). "IL-1β and IL-6 have been shown to stimulate BC cell proliferation in an additive manner with estrogen, indicative of synergy between inflammatory mediators and hormones within the mammary tumor microenvironment." (PMID 25360510, 2014). "Breast cancer patients exposed to adjuvant regional radiotherapy could have cognitive impairment, which might be partially mediated by the elevation of plasma IL-6 levels." (PMID 24756915, 2014). "BMI and leptin correlated with IL-6 levels in ER+ post-menopausal breast cancer patients." (PMID 25338520, 2014). "In this study, we demonstrated that IL-6 could drive EMT and promote metastasis in lung adenocarcinoma, similar to the function of IL-6 in breast cancer and head and neck tumor metastasis." (PMID 24789104, 2014). "Further, IL-6 has been shown to stimulate aromatase expression in adipose tissue; aromatase expression subsequently stimulates oestrogen synthesis, potentially contributing to breast cancer progression." (PMID 25305747, 2014). "For example, IL-6 was increased in patients suffering from colitis-associated cancer (CAC), and autocrine IL-6 signaling was shown to be critically involved in lung and breast cancer development." (PMID 24742922, 2014). "Accordingly, additional studies will be needed to determine whether MUC1-C also contributes to the regulation of IL-6 expression in breast cancer cells." (PMID 24770886, 2014). "A recent study revealed that IL-6 activated Jagged1/Notch1 signaling contributes to bone metastasis of breast cancer, indicating that multiple pathways may be involved in the IL-6-mediated CSC regulation." (PMID 26932376, 2014).
breast cancer (continued). "To examine the molecular mechanism by which senescent MSCs stimulate breast cancer cell proliferation and migration, we assessed four cytokines (IL-6, VEGF, HGF and TNF-α) that are closely related to tumor progression by enzyme linked immunosorbent assay (ELISA)." (PMID 25419563, 2014). "The high risk for early events observed in these subgroups of patients suggests that combined information on IL6 genotype, tumour ER-status, and breast cancer treatment may represent a tool for identifying patients who require more personalised treatment." (PMID 25305747, 2014). "In primary breast cancer, interleukin-6 (IL-6) induced activation of its downstream effectors, JAK2 and STAT3, and this signaling played a critical and pharmacologically targetable role in orchestrating the composition of the tumor microenvironment that promotes growth, invasion, and metastasis." (PMID 25405202, 2014). "Table-III shows that the mean serum levels of both TPA and IL-6 in the first group of breast cancer patients who received 6 cycles of chemotherapy were significantly lower than their levels in the control group of breast cancer patients who did not received chemotherapy yet." (PMID 25225536, 2014). "Thus, we concluded that IL-6 secreted from breast cancer cells is an important and sufficient factor for MDSC expansion and recruitment, but that additional factors are required to facilitate the recruited MDSC-mediated metastasis of cancer cells." (PMID 24021059, 2013). "We have shown that more MDSCs were recruited to the different organs of mice implanted in the mammary fat pads with high IL-6-producing breast cancer cells and the depletion of MDSCs by an anti-Gr1 antibody reduced the numbers of metastatic nodules in the lung." (PMID 24021059, 2013). "In our previous report, high IL-6-secreting human breast cancer cells revealed more aggressive phenotypes including enhanced distant metastasis and recruited more inflammatory cells (our unpublished data) compared to the low IL-6 expressing cells." (PMID 24021059, 2013). "This signaling pathway involving NF-κB/IL-6/STAT3 has been demonstrated to be important in the pathogenesis of various epithelial cancers associated with inflammation, especially gastrointestinal cancer and breast cancer." (PMID 23705069, 2013). "IL-6 has been shown to inhibit growth and enhance motility in breast cancer cell lines." (PMID 23426399, 2013). "In addition to the autocrine feedback mechanism, IL6 signaling pathways downregulate mir200c in a chemically-induced transformed breast cancer cell line." (PMID 23935876, 2013). "In addition, tumor-expanded MDSCs expressed Adam-family proteases, which facilitated shedding of IL-6 receptor, thereby contributing to breast cancer cell invasiveness and distant metastasis through IL-6 trans-signaling." (PMID 24021059, 2013). "IL-6 was found to be involved in tumor growth and metastasis spread by inducing expansion of MDSCs and immune suppression, and it can also affect the tumor parenchyma by inducing a more malignant, cancer stem cell phenotype in breast cancer cells." (PMID 24146823, 2013). "Since IL-6 reduces cell adhesion in breast cancer cells, a similar mechanism might affect the stability of cellular contacts between microglia, impairing gap junctional communication." (PMID 23737642, 2013). "We investigated the association between 89 single nucleotide polymorphisms (SNPs) in 7 cytokine/growth-factor genes (FGFR2, IGFBP1, IGFBP3, TGFB1, TNF, VEGF, IL6) and percent MD in 301 premenopausal women (aged 50 to 55 years) participating in the Norwegian Breast Cancer Screening Program." (PMID 23762340, 2013). "In addition, NFκB, an antiapoptotic transcription factor regulating IL-6 expression, is constitutively activated in breast cancer and contributes to CSC stemness and chemoresistance." (PMID 24392029, 2013).
breast cancer (continued). "Furthermore, elevated serum IL-6 levels correlate with advanced breast tumor stage, increased number of metastatic sites, and poor survival in patients with breast cancer." (PMID 22134360, 2012). "In this study, we examined levels of MCP-1, IL-6, KC, MIP-2, VEGF, MIG, and eotaxin in femurs of athymic nude mice inoculated via intracardiac injection with MDA-MB-231GFP human metastatic breast cancer cells, MDA-MB-231BRMS1GFP, a metastasis suppressed variant, or PBS." (PMID 22315691, 2012). "In colorectal and breast cancers, high IL6 expression was also associated with a high rate of lymph node metastasis." (PMID 23185547, 2012). "Nevertheless, other studies have detected and quantified IL6 expression in breast cancer." (PMID 23145063, 2012). "Moreover, the inactivation of gp130, a transducer of IL-6 signaling, reduced the aggressiveness of breast cancer cells in vivo." (PMID 22745766, 2012). "Increased IL6 expression in either serum, saliva, or tumor tissues has been noted in patients with colorectal cancer, breast cancer, lymphoma, hepatocellular carcinoma, pancreatic carcinoma, renal cell carcinoma, bladder cancer, and multiple myeloma and it has been implicated in tumor development." (PMID 23185547, 2012). "In breast cancer, IL-6 is known to activate STAT3, which has been shown to be an important signaling molecule that is associated with an unfavorable prognosis; in fact, the principal mechanism of STAT3 activation is via the IL-6/gp130/Jak pathway." (PMID 22235336, 2012). "This suggests a role of IL-6 in breast cancer stem cell biology." (PMID 22235336, 2012). "Moreover STAT3 is a potent mediator of pro-inflammatory interleukin 6 (IL-6) that was shown to induce EMT phenotype in human breast cancer cells." (PMID 22194995, 2011). "Moreover, we identify a novel tumor promoting mechanism of these cells that is enhanced upon exposure to PGE2: the ability to secrete factors (such as IL-6) that are essential for the expansion of CD44+/CD24−/EpCAM+ breast cancer cells." (PMID 21957456, 2011). "IL-6 production in human breast cancer cells was dependent on their TG2 expression level." (PMID 21967801, 2011). "Furthermore, by using public datasets that included a total of 684 breast cancer patients, we found that the combined high expression of TG2 and IL-6 was associated with shorter DMFS, compared with the high expression of IL-6 only (P = 0.013)." (PMID 21967801, 2011). "A correlation between in vitro tumor-sphere formation and in vivo tumorigenesis was confirmed in breast cancer cells, and TG2 expression and downstream IL-6 production were profoundly correlated with primary tumor growth of the human breast cancer cells in the mammary fatpads." (PMID 21967801, 2011). "In addition, bone metastatic breast cancer cells coopt native bone cells like the osteoblast to increase their production of the inflammatory cytokines IL-6, MCP-1, VEGF, MIP-2 (human IL-8), and KC (human GRO-α)." (PMID 21647291, 2011). "Thus the levels of IL-6 has a positive correlation with TNM staging system of breast cancer thus indirectly correlating with the prognosis of the patient." (PMID 21294915, 2011). "Thus TG2 and downstream IL-6 produced from epithelial breast cancer cells facilitated distant hematogenous lung metastases of these cells." (PMID 21967801, 2011). "Thus the levels of IL-6 correlates with all the aspects of breast cancer like tumour size lymph node involvement, distant metastasis and the final TNM staging of the disease." (PMID 21294915, 2011). "Thus, targeting either TG2 or downstream IL-6 would be a very efficient strategy to inhibit primary tumor growth and distant hematogenous metastasis of breast cancer cells." (PMID 21967801, 2011).